NLRC4 (NLR family CARD domain containing 4)
Diseases named in the same sentence as NLRC4 in open-access papers (continued):
Sharing a sentence is not in itself a finding about the gene and the disease.
Candida infection (2 papers, 2011 to 2020). "The cytokine IL-6 was induced in wild-type mice in response to Candida infection but was significantly reduced in NLRC4 deficient mice and completely abrogated in NLRP3 and ASC deficient mice." (PMID 22174673, 2011). "Borghi and colleagues demonstrated that an IL-22/NLRC4/IL-1 receptor antagonist (IL-1Ra) axis controls NLRP3 activation during Candida infection." (PMID 33119702, 2020). "Neutrophil influx into the Nlrc4-/- tongue was drastically reduced compared to either wild-type (wt) or Nlrp3-/- mice, and NLRC4 activation was crucial for the trafficking of neutrophils to the site of active Candida infection." (PMID 33119702, 2020). "Here we show that mucosal expression of NLRP3 and NLRC4 is induced by Candida infection, and up-regulation of these molecules is impaired in NLRP3 and NLRC4 deficient mice." (PMID 22174673, 2011). "Collectively, these studies reveal the tissue specific roles of the NLRP3 and NLRC4 inflammasome in innate immune responses against mucosal Candida infection." (PMID 22174673, 2011). "NLRC4 is important for control of mucosal Candida infection and impacts inflammatory cell recruitment to infected tissues, as well as protects against systemic dissemination of infection." (PMID 22174673, 2011). "Expression levels of CAMP were dramatically elevated in WT buccal tissue following Candida infection, and this induction was dependent on NLRC4, NLRP3 and ASC." (PMID 22174673, 2011). "Interesting patterns of induction of the IL-17 family by Candida infection were observed; IL-17A was dependent on NLRC4, NLRP3 and ASC whereas IL-17F was only dependent on NLRP3 with comparable induction seen in WT, NLRC4 and ASC deficient mice." (PMID 22174673, 2011). "A defect in pyroptosis may partially account for the critical role for NLRC4 activation in our model of candidiasis and provides an opportunity for future research." (PMID 22174673, 2011). "Taken together, our studies imply that NLRC4 and NLRP3 are differentially functioning in the innate response to Candida infection, with NLRC4 playing a more prominent role in the clearance of oral infection." (PMID 22174673, 2011). "We show that Candida infection up-regulates NLRP3 and NLRC4 expression in mucosal tissues compared to mock infected mice." (PMID 22174673, 2011). "We show that inflammasome driven IL-1β responses via both the NLRC4 and NLRP3 inflammasome are essential for epithelial antimicrobial peptide production, and other inflammatory responses including IL-18 and IL-17 in response to Candida infection." (PMID 22174673, 2011).
chronic myelogenous leukemia (2 papers, 2022). "The NLRP1 inflammasome was linked to multiple myeloma and chronic myeloid leukemia pathogenesis, whereas the NLRC4 was the key player in secondary HLH." (PMID 35897704, 2022).
corneal disease (2 papers, 2017 to 2023). "Overall, these findings support a role for NLRP3 and caspase-1 in regulating bacterial killing and corneal disease severity with no apparent role for NLRC4 and no requirement for GSDMD, GSDME, or neutrophil elastase." (PMID 37730693, 2023). "Also, in P. aeruginosa infection, NLRP3 and caspase-1, but not NLRC4 were required for IL -1β production, bacterial killing and corneal disease severity." (PMID 37730693, 2023).
Crohn disease (2 papers, 2021 to 2025). A gastrointestinal disorder characterized by chronic inflammation involving all layers of the intestinal wall, noncaseating granulomas affecting the intestinal wall and regional lymph nodes, and transmural fibrosis. "In addition, AIEC (adherent/invasive E. coli) are frequently found in patients with Crohn’s disease and have been implicated in intestinal inflammation via their capacity to simulate the NLRC4 inflammasome." (PMID 41246319, 2025). "Despite these limitations, the results of first study were clear in showing that circulating cells from patients with Crohn’s disease exhibited significantly higher mean NLRC4-induced IL-1β and IL-18 responses than cells from control individuals." (PMID 41246319, 2025). "In the present study, we explored the relation of LRRK2-kinase phosphorylation of the NLRC4 inflammasome to NLRC4 inflammasome function in normal humans and mice, as well as in patients with Crohn’s disease (CD)." (PMID 41246319, 2025). "The higher levels of NLRC4 inflammasome activity in patients with Crohn’s disease noted in our studies prompts a consideration of the role of this inflammasome in Crohn’s disease pathogenesis." (PMID 41246319, 2025).
dengue (2 papers, 2019 to 2025). "B7, Bacillus licheniformis, and Clostridium cochlearium, along with the host genes, namely, PPME1, TIMP2, NLRC4, and RhoB, were associated with immune dysregulation in the severe dengue patients." (PMID 41417796, 2025). "Moreover, a decrease in the expression of the inflammasome-related genes NLRP1, NLRC4, caspase-1, IL-1β and IL-18 was observed, as well as an increase in serum levels of C-reactive protein and IL-10 in dengue patients versus healthy donors." (PMID 30901375, 2019).
diabetes (2 papers, 2021 to 2023). "Further studies have shown that lncRNA-Fendrr promotes NLRC4-mediated pyroptosis in microglia model of diabetes-cerebral I/R, but HERC2 reversed the effect of lncRNA-Fendrr." (PMID 33858325, 2021). "Our study found that the restraint of lncRNA-Fendrr markedly reduced NLRC4, ASC, pro-caspase-1, and caspase-1 mediated pyroptosis in BV-2 cell model of diabetes-cerebral I/R." (PMID 33858325, 2021). "Perhaps NLRC4 does not have a correlation with other types of diabetes, and perhaps more experiments are still needed to explore." (PMID 36993972, 2023). "However, there are few studies on NLRC4 and T1DM or other types of diabetes." (PMID 36993972, 2023).
dry eye (2 papers, 2023 to 2024). "NLRP12/NLRC4 knockdown, GSDMD knockout, or the neutralization of mature IL-33 can obviously attenuate the damage to corneal epithelial cells, indicating that these molecules could be key targets for dry eye treatment in the future." (PMID 37250902, 2023).
endotoxemia (2 papers, 2022 to 2025). "For the first time, we found that L attenuated both HF diet-induced endotoxemia and NLRC4 activation in VAT." (PMID 40149869, 2025). "Endotoxemia and VAT inflammation may be just linked to increased NLRC4 expression." (PMID 40149869, 2025). "Only inhibition of both IL-18 and IL-1β completely protects against mortality in a murine model of lethal endotoxemia, and combined blockade of IL-18 and IL-1β has been successfully implemented in a genetic form of MAS resulting from NLRC4 inflammasome hyperactivity." (PMID 35190900, 2022).
enteritis (2 papers, 2024 to 2025). Inflammation of the small intestine. "It has been established that L. johnsonii L531 could alleviate Salmonella infantis-associated enteritis and promote intestinal secretory IgA production via regulation of NLRC4 and NLRP3 inflammasomes, NF-κB signaling pathway activation and suppression of mitochondrial damage." (PMID 39619663, 2024).
enteropathy (2 papers, 2021). "Hematoxylin and Eosin staining of cecal tissue revealed a progressing enteropathy in both the control and the NLRC4-deficient mice." (PMID 33731826, 2021). "In NAIP/NLRC4-deficient mice, S.Tm elicited severe enteropathy within 72 h, characterized by elevated mucosal TNF (>20 pg/mg) production from bone marrow-derived cells, reduced regeneration, excessive enterocyte loss, and a collapse of the epithelial barrier." (PMID 33731826, 2021).
fatty liver disease (2 papers, 2023). A reversible condition wherein large vacuoles of triglyceride fat accumulate in liver cells via the process of steatosis. "These include detailing an allelic series in NLRC4, identifying potential biomarkers for a fatty liver disease-associated variant in HSD17B13 and bolstering phenome-wide association studies by integrating protein quantitative trait loci with protein-truncating variants in collapsing analyses." (PMID 37794183, 2023).
Hashimoto thyroiditis (2 papers, 2020 to 2024). An autoimmune disorder caused by the production of autoantibodies against thyroid tissue. "Recently, a significant association of NLRC4 rs385076 with Hashimoto’s thyroiditis was identified for the first time." (PMID 38999993, 2024). "Hi-SNP high-throughput genotyping technology was used for detecting four single-nucleotide polymorphisms (SNPs) of NLRC4 in 1005 AITDs patients (including 629 Graves' disease and 376 Hashimoto's thyroiditis) and 781 healthy controls." (PMID 32802832, 2020). "Activation of the inflammasome by IL-β and IL-18 produced by macrophages is one of the mechanisms of pyroptosis in the course of Hashimoto’s thyroiditis, involving Gram-negative bacteria and NLRC4." (PMID 38999993, 2024).
heart failure (2 papers, 2024 to 2025). Inability of the heart to pump blood at an adequate rate to meet tissue metabolic requirements. "Interestingly, AIM2 and NLRC4 were found elevated in cardiac lymphoid cells of failing human hearts; while expression of AIM2 was found in an experimental rodent model of heart failure, further suggesting a role of the inflammasome in the context of adverse cardiac remodeling and heart failure." (PMID 39556309, 2025).
hematoma (2 papers, 2021 to 2023). A hematoma is a collection of blood from a vascular structure into an extravascular space. "Nomograms were built to reflect prognosis and END risk of combination models, where serum NLRC4, NIHSS scores and hematoma volume were enforced." (PMID 36970543, 2023). "NIHSS scores, hematoma volume and NLRC4 levels >363.2 pg/ml were combined to differentiate between good prognosis and poor prognosis, whose predictive ability was indicated by a nomogram." (PMID 36970543, 2023). "Immunostaining (× 200 and × 400) results showed that NLRC4 siRNA treatment reduced MPO-positive cells around the hematoma compared to the ICH group." (PMID 34848837, 2021). "Using the four multivariate regression models, we revealed the close relationship between serum NLRC4 levels and NIHSS scores, hematoma volume, 6-month mRS scores, END in addition to 6-month poor prognosis after human ICH." (PMID 36970543, 2023). "In terms of predictive ability for 6-month poor outcome, serum NLRC4 levels combined with NIHSS scores and hematoma volume was superior to NIHSS scores combined with hematoma volume, NIHSS scores and hematoma volume (AUC, 0.913 vs. 0.870, 0.864 and 0.835; all P < 0.05)." (PMID 36970543, 2023). "More intriguingly, serum NLRC4 levels combined with NIHSS scores and hematoma volume had significantly higher prognostic predictive ability, but not substantially higher END predictive ability, than NIHSS scores, hematoma volume, and combination of NIHSS scores with hematoma volume." (PMID 36970543, 2023).
hepatocellular carcinoma (2 papers, 2019 to 2022). A malignant tumor that arises from hepatocytes. "The NLRC4 inflammasome activates Caspase-1 via the canonical inflammasome pathway of pyroptosis, triggering cell pyroptosis, thus forming a novel SMS1-DAGPKCδ-NLRC4 axis, which induces hepatoma pyroptosis." (PMID 35411030, 2022).
Hypertension (2 papers, 2022). The presence of chronic increased pressure in the systemic arterial system. "NLRC4 is capable of forming inflammasome complexes has been identified to play a role in hypertension." (PMID 36620210, 2022). "For instance, our group demonstrated that the increased expression of inflammasome genes, including the flagellin sensor Nod-like receptor (NLR) family caspase recruitment domain (CARD)-containing protein 4 (NLRC4) and IL-1β are strong predictors of hypertension and arterial stiffness." (PMID 36364734, 2022). "Among several types of inflammasomes NLR family CARD domain-containing protein 4 (NLRC4), NLRP6 and NLRP9, NLRP3 is most studied inflammasome in hypertension." (PMID 36620210, 2022).
influenza (2 papers, 2022 to 2025). An acute viral infection of the respiratory tract, occurring in isolated cases, in epidemics, or in pandemics; it is caused by serologically different strains of viruses (influenzaviruses) designated A, B, and C, has a 3-day incubation period, and usually lasts for 3 to 10 days. "Recently, influenza has been shown to activate NLRC4 which regulates influenza-specific T cells." (PMID 36298668, 2022). "Multiple inflammasomes can be involved in IL-1β activation, including NLRP3, NLRP1, NLRC4, AIM2, IFI16 and RIG-I, however because GC B cells are not directly infected by influenza infection, we examined NLRP3 and AIM2 as they are activated by stimuli likely to be present in GC B cells." (PMID 40825032, 2025).
ischemia (2 papers, 2020 to 2022). A hypoperfusion of the BLOOD through an organ or tissue caused by a PATHOLOGIC CONSTRICTION or obstruction of its BLOOD VESSELS, or an absence of BLOOD CIRCULATION. "Besides NLRP3, AIM2 and NLRC4 seem to play a crucial role after ischemia and are regulated by E2 and P." (PMID 32645874, 2020). "Poh and colleagues provided evidence in 2019 that NLRC4 inflammasomes mediate both the inflammatory response, as well as apoptotic and pyroptotic cell death in murine microglial cells subjected to in vitro and in vivo ischemia." (PMID 32645874, 2020). "We demonstrate that AIM2 and NLRC4 are upregulated after ischemia and E2 + P seem to downregulate AIM2, while NLRC4 seems to be lowered only by E2." (PMID 32645874, 2020). "To further investigate and validate our in vivo findings, we examined microglial cells and astrocytes in an in vitro ischemia model with respect to AIM2 and NLRC4 expression." (PMID 32645874, 2020). "Moreover, functional inhibition of NLRP3 is compensated by an upregulation of NLRC4 and AIM2 after ischemia." (PMID 34628598, 2022). "NLRC4 inflammasomes in astrocytes did not appear to be influenced by OGD or the steroid hormones E2 and P, indicating a minor role of NLRC4 in primary cortical astrocytes after in vitro ischemia." (PMID 32645874, 2020).
Latent infections (2 papers, 2019 to 2021). "In normal to latent infections, we identified eight genes, of which three genes (FZD2, NDUFS8, NLRC4) were up-regulated, and another five genes (CCL4, IL1B, IL1A, TNF, AREG) were down-regulated." (PMID 31749827, 2019).
leukemia (2 papers, 2022 to 2024). A malignant (clonal) hematologic disorder, involving hematopoietic stem cells and characterized by the presence of primitive or atypical myeloid or lymphoid cells in the bone marrow and the blood. "In this study, we demonstrated that curcumin induced the expression of AIM2, IFI16, and NLRC4 inflammasomes in leukemia cells U937 by increasing the expression levels of ISG3 transcription factor complex, which activated caspase 1, promoted cleavage of GSDMD, and induced pyroptosis." (PMID 35435150, 2022). "In summary, here we have discovered that curcumin can induce leukemia cell death by increasing apoptosis and pyroptosis and that activated AIM2, IFI16, and NLRC4 inflammasomes play a key role in this process." (PMID 35435150, 2022). "In this study, we found that curcumin induced the expression of NLRC4, AIM2, and IFI16 inflammasomes by upregulated ISG3 transcription factor complex in leukemia cell U937, which activates caspase 1 and promotes cleavage of GSDMD." (PMID 35435150, 2022).
metastatic disease (2 papers, 2012 to 2014). "Recently, however, comparative mutational genomic analysis of samples taken from a patient with ENB at the time of initial presentation and following recurrent metastatic disease showed new acquired mutations in KDR, MYC, SIN3B, and NLRC4 genes with disease progression." (PMID 24672769, 2014). "However, in the original surgical resection specimen (prior to evidence of metastatic disease), mutations in KDR, MYC, SIN3B, and NLRC4 genes were not present, suggesting that these were acquired with disease progression and/or as a result of post-treatment effects." (PMID 22649506, 2012).
non-alcoholic fatty liver disease (2 papers, 2022 to 2023). "Furthermore, loss of NLRC4 impeded colon cancer liver metastasis accompanied by reduced infiltration level of M2 macrophages and IL-1β expression in mice with high-fat diet-triggered nonalcoholic fatty liver disease (NAFLD)." (PMID 36920176, 2023). "For instance, the NLRP1-IL-18 pathway was shown to promote the generation of mature MDSCs in multiple myeloma, and the Nlrc4 inflammasome in controlling CRC metastasis to the liver in non-alcoholic fatty liver disease (NAFLD)." (PMID 35517498, 2022).
peritonitis (2 papers, 2018 to 2025). Inflammation of the peritoneum (tissue that lines the abdominal wall and covers most of the organs in the abdomen). "CLANmCas9/gNLRP3 was unable to entirely prevent septic shock and peritonitis likely because of the activation of other inflammasomes, such as NLRP1, NLRC4, and AIM23,5,7, and the inactivation of the NLRP3 inflammasome was insufficient to inhibit acute inflammation." (PMID 30291237, 2018).
prostate carcinoma (2 papers, 2017 to 2021). A carcinoma that arises from epithelial cells of the prostate gland. "Using Gene Expression Omnibus (GEO) public datasets, we screened the expression profiles of inflammasome sensors NLRP3, NLRC4, NLRP6, NRLP12, and AIM2 in prostate tumor tissues, and verified their mRNA level in a panel of prostate cancer cell lines." (PMID 28663562, 2017). "We found that the mRNA level was very much variable across the cell lines, and there was no consensus on the expression levels of NLRP3, NLRC4, NLRP6, and AIM2 among early stage (e.g. LNCaP and LNCaP-Ln3) and late stage (e.g. PC3 and DU145) prostate cancer cell lines." (PMID 28663562, 2017).
renal fibrosis (2 papers, 2023 to 2024). A final common manifestation of a wide variety of chronic kidney diseases characterized by glomerulosclerosis and tubulointerstitial fibrosis. "Whereas we found that the expression levels of NLRC4 inflammasome and fibrosis related proteins were decreased in SHR-M group, indicating MICT reduced renal fibrosis in SHR by inhibiting the activation of NLRC4 inflammasome." (PMID 39052650, 2024). "Additionally, NLRC4 is one of the hub genes involved in myofibroblasts generation, inflammation, and pyroptosis in renal fibrosis, indicating that NLRC4 is a potential target to inhibit the progression of renal fibrosis." (PMID 37500614, 2023). "However, the putative activation processes and function of the NLRC4 inflammasome in renal fibrosis remain unknown." (PMID 37500614, 2023). "We also found that MICT alleviated renal fibrosis and inflammatory response as well as inhibited TLR4/NF-κB pathway and the activation of NLRC4 inflammasome in SHR." (PMID 39052650, 2024). "MICT improved renal fibrosis and renal injury, attenuating the inflammatory response by inhibiting TLR4/NF-κB pathway and the activation of NLRC4 inflammasome." (PMID 39052650, 2024). "MICT ameliorated renal damage, inflammatory response, and renal fibrosis via repressing TLR4/NF-κB pathway and the activation of NLRC4 inflammasome." (PMID 39052650, 2024).
schizophrenia (2 papers, 2022 to 2025). A major psychotic disorder characterized by abnormalities in the perception or expression of reality. "A recent report showed that increased expression of NLRP3 and NLRC4, together with high baseline levels of circulating components of IL-18, was observed in the blood of patients with schizophrenia and bipolar disorder compared with healthy controls." (PMID 35546942, 2022).